BRCA2 (BRCA2 DNA repair associated)
Diseases named in the same sentence as BRCA2 in open-access papers (continued):
Sharing a sentence is not in itself a finding about the gene and the disease.
invasive breast carcinoma (49 papers, 2005 to 2025). A carcinoma that infiltrates the breast parenchyma. "In each group, seven patients underwent prophylactic mastectomy because of a BRCA1 or BRCA2 gene mutation, while four patients underwent mastectomy following a diagnosis of invasive breast cancer." (PMID 40788543, 2025). "Dysregulation of let-7b has also been observed in BRCA2 germ-line mutation carriers between invasive breast cancer and asymptomatic normal breast tissue." (PMID 37019900, 2023). "The proportion of BRCA1 and BRCA2 mutation carriers is high among patients with young-onset (aged 18–40 years) invasive breast cancer cancer." (PMID 37644384, 2023). "While BRCA1/BRCA2 pathogenic sequence variants (PSVs) clearly confer an increased risk for invasive breast cancer, the extent to which these mutant alleles increase DCIS risk is less clear." (PMID 36349178, 2022). "From January 2003 till March 2019, 62 invasive breast cancers and 23 ductal carcinomas in situ were diagnosed in 83 BRCA2 mutation carriers under surveillance." (PMID 32333294, 2020). "We studied 608 women with invasive breast cancer and a pathogenic BRCA2 mutation (variant) from four Nordic countries." (PMID 32939053, 2020). "The 148 patients were identified until June 2003 as carrying BRCA1 or BRCA2 mutations with previous histories of unilateral, stage I–IIIa invasive breast cancer." (PMID 30203341, 2018). "Data from 3750 country-matched female BRCA2 mutation carriers diagnosed with invasive breast cancer were included in this analysis." (PMID 26857456, 2016). "Let-7b was found to be specifically deregulated between invasive breast carcinomas and asymptomatic normal breast tissues in BRCA2 germ-line mutation carriers." (PMID 26378051, 2015). "Let-7b was found to be specifically down-regulated in invasive breast carcinomas of BRCA2 germ-line mutation carriers." (PMID 26378051, 2015). "A more recent study from the same group, found that 5.3% of French Canadian women with invasive breast cancer had one of six recurrent BRCA1/BRCA2 mutations." (PMID 25925845, 2015). "Although BRCA1 and BRCA2 germline mutation-related invasive breast cancers are different in many ways, the hypoxia-related proteins HIF-1α, CAIX and Glut-1 are expressed in both DCIS and invasive lesions of BRCA1 and BRCA2 mutation carriers." (PMID 23409121, 2013). "We also examined the association with rs2180341 in women with BRCA1 or BRCA2 mutations based on data from 2,776 invasive breast cancer cases and 2,605 unaffected carriers." (PMID 22768030, 2012). "9,815 BRCA1 and BRCA2 mutation carriers were censored at a first invasive breast cancer diagnosis, of whom 4,310 had information on either ER or PR." (PMID 22053997, 2011). "The prevalence of BRCA1 and BRCA2 mutations among all women diagnosed with an invasive breast cancer or ductal carcinoma in situ is similar, and varies between 0.4–2.6% and 1.4–2.4%, respectively." (PMID 16909138, 2006). "We identified a cohort of 148 female BRCA1 or BRCA2 mutation carriers (115 and 33, respectively) who previously were treated for unilateral invasive breast cancer stages I–IIIa." (PMID 16052221, 2005). "Given the diagnosis of invasive breast cancer and BRCA2 mutation carrier status, our proband opted for prophylactic bilateral salpingo-oophorectomy with hysterectomy, as well as removal of the nipple-areola complex along with remaining breast tissue." (PMID 16079000, 2005). "In one family with a germline BRCA2 mutation, three cases of invasive breast cancer and one case of DCIS were observed." (PMID 16280055, 2005). "Therefore, in the present study, the efficacy of CPM was investigated in a group of women with pathogenic BRCA1 or BRCA2 mutations and a personal history of unilateral invasive breast cancer." (PMID 16052221, 2005). "The clinical outcome of contralateral prophylactic mastectomy (CPM) in women with a BRCA1 or BRCA2 mutation and a personal history of invasive breast cancer is unknown." (PMID 16052221, 2005).
invasive breast carcinoma (continued). "In contrast, BRCA2 and PALB2-associated invasive breast cancers were more likely to be node-positive and were ER + HER2- in 63.2–70% of cases." (PMID 40275390, 2025). "We set up cohorts of patients with invasive breast cancers and documented germ-line BRCA1 and BRCA2 pathogenic variant statuses." (PMID 32290274, 2020). "We sought to identify factors that predicted survival after invasive breast cancer in an expanded cohort of BRCA2 carriers." (PMID 32939053, 2020). "BRCA2 c.68‐7T > A was identified in 242/41,890 (0.58%) invasive breast cancer cases and 216/41,746 (0.52%) controls of reported European ancestry recruited through BCAC studies." (PMID 29460995, 2018). "Twelve carriers had a history of invasive breast cancer and chemotherapy (nine BRCA1 and three BRCA2 mutation carriers), and 51 carriers were excluded for other reasons." (PMID 28831696, 2017). "The analysis was restricted to carriers diagnosed with invasive breast cancer (326 BRCA2 and 40 BRCA1)." (PMID 26857456, 2016). "The sensitivity and specificity of evaluating serum anti-BRCA2 AAbs were 34% and 92%, respectively, for invasive breast carcinoma, and 23% and 92%, respectively, for ductal carcinoma in situ." (PMID 21113302, 2010). "AAbs to BRCA1 and BRCA2 protein were identified by ELISA in the sera of 8/94 (8.5%) and 32/94 (34%) invasive breast carcinoma patients, respectively, and 1/40 (2.5%) and 9/40 (22.5%) ductal carcinoma in situ patients, respectively." (PMID 21113302, 2010). "We report a case of invasive breast cancer in a BRCA2-positive woman 33 years after bilateral subcutaneous mastectomy." (PMID 16079000, 2005). "We collected clinical information for BRCA2 mutation carriers with invasive breast cancer from four Nordic countries (Denmark, Iceland, Norway and Sweden)." (PMID 32939053, 2020). "Using TCGA publicly available expression profiles of cancer patients, we found that BRCA1 and BRCA2 were widely expressed in multiple tumors compared with normal tissues, including breast invasive carcinoma (BRCA), liver hepatocellular carcinoma (LIHC), and rectum adenocarcinoma (READ)." (PMID 32879886, 2020). "All miRNAs selected for qRT-PCR validation, except miR-1287, were differentially expressed in the same direction in qRT-PCR as in microarray analysis between the invasive breast carcinomas and the asymptomatic normal breast tissues of BRCA1 and BRCA2 germ-line mutation carriers." (PMID 26378051, 2015). "The authors suggest that DCIS and LOH in the BRCA2 locus may be common early steps in the development of invasive breast cancer in BRCA2 carriers." (PMID 16280055, 2005). "To investigate the value for FOXPs to distinguish Breast Invasive Carcinoma samples from normal smples, we performed a ROC curve analysis using ERBB2, BRCA1 and BRCA2 as controls." (PMID 35614183, 2022). "Analyses was restricted to the 392 (BRCA1) and 179 (BRCA2) population-based individuals diagnosed with a first primary invasive breast cancer before 40 years of age for whom BRCA1 and BRCA2 had been sequenced." (PMID 20807450, 2010). "This case report describes a 56-year-old female with invasive breast cancer without estrogen or progesterone receptor expression, with apocrine differentiation, and with no germline variants in the BRCA1 and BRCA2 genes." (PMID 37583932, 2023). "Interestingly, a positive correlation between ATM, ATR, BRCA1, BRCA2, and KMT2C expression is also derived from TCGA data GBM, LGG, AML, DLBL, SARC, and breast invasive carcinoma (BRIC) RNA‐seq data." (PMID 30665945, 2019). "A total of 8396 patients (mean [SD] age, 50.8 [11.4] years) with primary invasive breast cancer (stages I-III), including 491 BRCA1/2 variant carriers (5.8%) (187 BRCA1 carriers [2.2%] and 304 BRCA2 carriers [3.6%]) and 7905 noncarriers (94.2%), were included in the final analyses." (PMID 33890992, 2021).
male breast carcinoma (49 papers, 2004 to 2026). A malignant neoplasm involving the male breast. "Male breast cancer (mBC) is a rare disease associated with a high prevalence of pathogenic germline variants (PVs) in the BRCA2 gene." (PMID 35805063, 2022). "Male breast cancer linked to a mutation in the BRCA2 gene occurs earlier and has a poorer prognosis." (PMID 32934847, 2020). "Inherited mutations in BRCA1, and, mainly, BRCA2 genes are associated with increased risk of male breast cancer (MBC)." (PMID 30564557, 2018). "Five patients had family history of male breast cancer, two (40.0%) of them had deleterious/suspected deleterious mutations in BRCA2, another patient harbored a VUS in BRCA2." (PMID 29409476, 2018). "Several risk factors including advancing age, positive family history and mutations in susceptibility genes such as BRCA1 and especially BRCA2 are considered for the study of male breast cancer." (PMID 27478808, 2016). "BRCA1 and, more commonly, BRCA2 mutations are associated with increased risk of male breast cancer (MBC)." (PMID 26857456, 2016). "BRCA2 mutations are considered the major genetic risk factor for male breast cancer, conferring a lifetime cumulative risk to develop the disease of about 9%, but the frequency of these mutations varies considerably between different populations." (PMID 27532258, 2016). "BRCA2 was originally identified as a tumor suppressor, as germline mutation of the BRCA2 gene results in a high risk of developing breast, ovarian, pancreatic, prostatic, and male breast cancer." (PMID 21779174, 2011). "Given the relatively unique nature of the link between BRCA2 mutations and male breast cancer, we therefore sought evidence of a functional interaction between BRCA2 and CHEK2." (PMID 18797466, 2008). "Male breast cancer is significantly associated with BRCA2 mutations." (PMID 26489409, 2015). "There have been associations with the BRCA2 gene mutation in many cases of male breast carcinoma." (PMID 23056988, 2012). "Our studies suggest a potential functional link between the CHEK2 kinase and the BRCA2 tumour suppressor, which may explain in part the increased incidence of male breast cancer observed in families with germline mutations in both of these genes." (PMID 18797466, 2008). "BRCA1, along with the BRCA2 gene which is more prevalent in male breast cancer, is a tumor suppressor that helps repair DNA double-strand breaks and decrease the amount of rapid cancerous growth in cells." (PMID 38137912, 2023). "Male breast cancer was the second most common cancer seen in 9 patients, all of whom were BRCA2 positive." (PMID 29433453, 2018). "Although BRCA2 is the most clearly associated gene, BRCA1 mutation is also considered in familial and even sporadic cases of male breast cancer." (PMID 27478808, 2016). "P/LP variants in BRCA1, BRCA2, PALB2, CHEK2, and ATM have been associated with male breast cancer." (PMID 39858629, 2025). "In Taiwan, there has been no prior investigation addressing BRCA2 mutations in male breast cancer (MBC)." (PMID 38275884, 2024). "Even though male breast cancer (MBC) risk encompasses both genetic and environmental aetiologies, the primary risk factor is a germline pathogenic variant (PV) or likely pathogenic variant (LPV) in BRCA2, BRCA1 and/or PALB2 genes." (PMID 37762649, 2023). "Subsequently, BRCA2 was considered a candidate gene because of the presence of male breast cancer, but no mutations were found in either BRCA1 or BRCA2 by screening of the full coding sequences of these genes with dHPLC and large rearrangement testing by MLPA." (PMID 19493351, 2009).
male breast carcinoma (continued). "Specifically, individuals with positive family history (especially those who are BRCA1/BRCA2 mutation negative), patients with bilateral disease, and patients with a family history of male breast cancer had a higher occurrence of 1100delC variants as compared with control individuals." (PMID 15535844, 2004). "In a retrospective analysis of 715 cases of male breast cancer, BRCA2 and CHEK2 were the most frequently involved genes in hereditary male breast cancer." (PMID 39858629, 2025). "Male breast cancer was absent in the BRCA1 c.676delT pedigrees, but was recorded for the BRCA2 c.7806-2A > G in 7 out 18 (39 %) families." (PMID 26852130, 2016).
colon carcinoma (45 papers, 2001 to 2025). "To determine the molecular effects of BRCA2 loss on telomere homeostasis, we analyzed the isogenic system of colon cancer cell line DLD1 bearing homozygous knockout for BRCA2." (PMID 31510074, 2019). "The family with the c.2639_2640delTG mutation in BRCA2 (patient 15) had a strong history of cancer, including laryngeal, gastric, lung and colon cancer in second- and third-degree relatives in the maternal branch." (PMID 22655046, 2012). "Our patient had a genomic instability-causing BRCA2 mutation which might have played a crucial role in increasing the risk for the development of colon cancer in this young patient." (PMID 39156267, 2024). "Four patients carrying BRCA2 variants had rectal cancer, and three had colon cancer." (PMID 37306523, 2023). "In addition, one patient with stage IV colon cancer carrying a deleterious variant of somatic BRCA2 mutation received maintenance PARPi using olaparib and had stable disease for 7.8 months." (PMID 33054725, 2020). "Thus, BRCA2 mutations probably contribute to gastrointestinal tumorigenesis other then colon cancer, and the surveillance scheme for mutation carriers should incorporate this information." (PMID 11207041, 2001). "Although there is still no consensus on the association between BRCA1/2 mutations and CRC, there is the suggestion that BRCA1 is associated with an increased risk of early-onset colon cancer but the association between CRC and BRCA2 mutation remains uncertain." (PMID 39156267, 2024). "FHL2 has been reported to play important roles in different cells’ differentiation, including neuronal cells, gastric and colon cancer cells, and limb mesodermal progenitors, and BRCA2 regulates the differentiation of both normal tissues and different cancers." (PMID 36428735, 2022). "ALT has been reported to be present in 10–15% of human cancers, including GSCs, but also in colon cancer cells with BRCA2 deletion or hereditary and sporadic colon cancer." (PMID 33260962, 2020). "TERRA hypertranscription was also confirmed in a HCT116 colon cancer cell line stably transfected with shRNA against BRCA2 or scrambled sequence." (PMID 31510074, 2019). "We tested miR-19a/miR-19b:BRCA2 interactions in 15 cell lines derived from pancreatic, breast, colon cancers, and kidney." (PMID 27630665, 2016). "In addition, PDSI exerted a greater cytotoxic effect in BRCA2-mutant than in BRCA2-proficient colon carcinoma cells." (PMID 34073075, 2021). "Here we will address the point if BRCA2 deletion could affect ALT dependent telomere maintenance in an isogenic cell model of colon cancer." (PMID 31510074, 2019). "We next determined chlorambucil anti‐tumour activity using paired BRCA2+/+ and BRCA2−/− HCT116 colon carcinoma cell lines, generated in one of our laboratories." (PMID 31273933, 2019). "Here we demonstrate that BRCA2 deletion triggers TERRA hyperexpression and alternative lengthening mechanisms (ALT) in colon cancer cells in presence of telomerase activity." (PMID 31510074, 2019). "We are grateful to Dr. Scott Kern for his generous gift of recombinant colon cancer cell lines RKO (FANCC parent), FCH3C12 (FANCC het +/−/−), FCE11C12 (FANCC null (−/−/−), DLD1 (BRCA2 parent), A9.A2 (BRCA2 het +/−) and A10.A3 (BRCA2 null −/−)." (PMID 27616351, 2016). "One recent study shows BRCA2 deletion triggers TERRA hyperexpression and alternative lengthening mechanisms (ALT) in colon cancer in presence of telomerase activity, which opens the question if patients bearing BRCA2 mutation suitable for anti-telomerase therapies." (PMID 35860598, 2021).
endometrial cancer (45 papers, 2011 to 2025). Primary or metastatic malignant neoplasm involving the endometrium (mucous membrane that lines the endometrial cavity). "The pathogenic mutation in ATM gene identified in this study (c.2502_2503insA) was found in a patient with family history positive for PanC and endometrial cancer, who presented also the BRCA2 pathogenic variant c.8954_8955delTTinsAA." (PMID 36717774, 2023). "We confirmed the significant association between pathogenic-likely pathogenic variants in BRCA2 and the increase of PanC risk, with variants identified more frequently among patients with a positive family history of endometrial cancer." (PMID 36717774, 2023). "The presence of mutations in BRCA2 was significantly associated with an increased occurrence of PanC and with positive family history for endometrial cancer (p = 0.018)." (PMID 36717774, 2023). "In the present study, we identified a BRCA2 germline mutation, p.T587fs, in patient with endometrial cancer." (PMID 35428225, 2022). "A sensitivity test showed that BRCA2 mutation increases the incidence of endometrial cancer grouped with other gynaecological cancers (RR 1.74 [1.17–1.58], data not shown)." (PMID 34577828, 2021). "BRCA1 and BRCA2 mutations were put together for analysis; most studies were case-control studies, and cases were selected amongst patients with endometrial carcinoma." (PMID 34577828, 2021). "The ESMO clinical practice guidelines for cancer prevention and screening in BRCA mutation carriers report that the association between BRCA1/BRCA2 mutations and an elevated risk of endometrial cancer remains weak." (PMID 32655641, 2020). "The study also included the largest number of BRCA2 pathogenic variant carriers to date, increasing our understanding of endometrial cancer risk in this specific population." (PMID 32698099, 2020). "An association between BRCA pathogenic variants and an increased endometrial cancer risk, specifically serous-like endometrial cancer, has been postulated but remains unproven, particularly for BRCA2 carriers." (PMID 32698099, 2020). "Loss of BRCA2 function in ovarian and endometrial cancer was associated with increased sensitivity to cisplatin, so patients with DDR alterations are thought to be sensitive to platinum agents." (PMID 31631483, 2019). "Interestingly, the BRCA1 and BRCA2 variants also were associated with high grade of endometrial carcinoma in the identified carriers." (PMID 39400928, 2025). "Therefore, more corroborating data and precision around endometrial cancer risk are needed before hysterectomy in BRCA1 or BRCA2 carriers can be routinely advocated." (PMID 34672090, 2022). "In one study of 199 Ashkenazi Jewish patients with endometrial cancer, the frequency of germ-cell line BRCA1 and BRCA2 mutations (3 per 199, 1.5%) in endometrial cancer patients was comparable to the baseline rate of 2% in the Ashkenazi population, suggesting no increased risk." (PMID 22518164, 2012). "In addition, although the small sample size did not allow to make conclusions on the associations with most of the clinical variables, including overall survival and therapies, we found that the presence of BRCA2 mutations was associated with positive family history for endometrial cancer." (PMID 36717774, 2023). "Debate, therefore, continues within the scientific and medical communities as to whether risk-reducing hysterectomy should be offered to women with BRCA1 and BRCA2 pathogenic variants at the time of their RRSO to reduce their subsequent endometrial cancer risk." (PMID 32698099, 2020). "In this cohort study of 1,083 women, there were five incident cases of serous/serous-like endometrial carcinoma that occurred after RRSO, four in BRCA1 mutation carriers, and one in BRCA2 mutation carriers." (PMID 38297203, 2024).